NDUFA2 (NADH:ubiquinone oxidoreductase subunit A2)
Description:
Accessory subunit of the mitochondrial membrane respiratory chain NADH dehydrogenase (Complex I), that is believed not to be involved in catalysis. Complex I functions in the transfer of electrons from NADH to the respiratory chain. The immediate electron acceptor for the enzyme is believed to be ubiquinone.
Synonyms: B8; CIB8; MC1DN13
Tractability: Small molecule: an approved drug acts on it; a structure with a bound ligand is known. Antibody: UniProt places it where antibodies can reach, with high confidence. PROTAC: ubiquitination databases record sites on it; its protein half-life has been measured.
Gene: Protein-coding gene on chromosome 5 (140,638,740 to 140,647,771, reverse strand). Ensembl gene ENSG00000131495.
Subcellular location: Mitochondrion inner membrane
Subcellular location (Human Protein Atlas): Mitochondria
Pathways (Reactome):
Metabolism: Complex I biogenesis; Respiratory electron transport
Metabolism of proteins: Mitochondrial protein degradation
Gene Ontology:
Molecular function: NADH dehydrogenase (ubiquinone) activity
Biological process: aerobic respiration; mitochondrial electron transport, NADH to ubiquinone; proton motive force-driven mitochondrial ATP synthesis; proton transmembrane transport
Cellular component: mitochondrial inner membrane; mitochondrial membrane; mitochondrion; respiratory chain complex I
Genetic constraint (gnomAD): Loss-of-function variants: 9 observed, 11.68 expected, observed/expected ratio (o/e) 0.77, 90% interval 0.46 to 1.34. The upper end of that interval is the gene's LOEUF score, 1.34, which puts it in group 5 of 6, group 1 being the genes least tolerant of losing a copy. Missense variants: 150 observed, 132.08 expected, observed/expected ratio (o/e) 1.14, 90% interval 0.99 to 1.3. Synonymous variants: 49 observed, 53.6 expected, observed/expected ratio (o/e) 0.91, 90% interval 0.73 to 1.16.
Gene-disease validity (ClinGen):
ClinGen rates the evidence that NDUFA2 causes each of these diseases.
mitochondrial disease (autosomal recessive): Definitive.
Leigh syndrome (autosomal recessive): Moderate. A progressive neurological disease defined by specific neuropathological features associating brainstem and basal ganglia lesions.
Homologues: Orthologues: macaque NDUFA2 (98% identical), rabbit NDUFA2 (97% identical), guinea pig NDUFA2 (96% identical), dog NDUFA2 (86% identical), mouse Ndufa2 (86% identical), rat Ndufa2 (84% identical), rat LOC120099907 (78% identical), pig NDUFA2 (73% identical), tropical clawed frog ndufa2 (72% identical), chimpanzee NDUFA2 (70% identical), zebrafish ndufa2 (67% identical), Caenorhabditis elegans ndua-2 (45% identical), and 1 more.
Diseases named in the same sentence as NDUFA2 in open-access papers:
NDUFA2 is named in the same sentence as 29 diseases in open-access papers, as found by Europe PMC text mining. Sharing a sentence is not in itself a finding about the gene and the disease. The quoted sentences say what the papers report.
Alzheimer disease (6 papers, 2016 to 2024). A progressive, neurodegenerative disease characterized by loss of function and death of nerve cells in several areas of the brain leading to loss of cognitive function such as memory and language. "MR of expression in brain cortex tissue showed that decreased MCI-related gene (NDUFA2) expression was associated with lower Alzheimer’s disease risk (OR 0.95, p=4.64×10−4) and favourable cognitive function." (PMID 35902387, 2022). "In this study, we also found that inhibition of expression of an MCI-related gene, NDUFA2, in brain cortex was linked with reduced Alzheimer’s disease risk and maintained cognitive function, providing human genetics evidence to ease such concerns." (PMID 35902387, 2022). "We reveal the independent role of inhibition of MCI on reducing Alzheimer’s disease risk and identified a mitochondrial-related gene, NDUFA2, as a key mediator in the brain." (PMID 35902387, 2022). "Reduced NDUFA2 expression has also been identified as a potential biomarker for Alzheimer’s disease, with an associated immune infiltration." (PMID 36499081, 2022). "Decreased expression level of an MCI-related gene, NDUFA2, in brain cortex was associated with reduced Alzheimer’s disease risk (OR 0.95, p=4.64×10−4) and maintained cognitive function (β 0.04, p=4.09×10−4)." (PMID 35902387, 2022). "Our candidate gene analysis suggested a causal role for the expression level of an MCI-related gene, NDUFA2, on Alzheimer’s disease and cognitive function, with this effect likely to be localised in brain." (PMID 35902387, 2022). "An observational study suggested NDUFA2 as a biomarker for Alzheimer’s disease." (PMID 35902387, 2022). "UK: United Kingdom; MR: Mendelian randomization; MCI: Mitochondrial complex 1; NDUFA2: MCI-related gene; AD: Alzheimer's disease." (PMID 38756263, 2024).
Leigh syndrome (4 papers, 2012 to 2025). "A loss-of-function mutation of NDUFA2 leads to Leigh disease, which is characterized by neurodegeneration." (PMID 40926280, 2025). "Variants related to Complex I such as NDUFS8, NDUFS7, and NDUFA2 are found to be explanations for Leigh syndrome, a neurodegeneration showing degenerative foci in the central neural system." (PMID 36431159, 2022). "Biallelic variants in nuclear gene NDUFA2 have been reported so far in only three children with variable presentations including Leigh syndrome or leukoencephalopathy." (PMID 32154054, 2020). "For example: Huntington’s disease (NDUFA7, NDUFC1, NDUFB2, NDUFB3, NDUFA8), atrophy of optic nerve (NDUFS4) and Leigh syndrome (NDUFS7, NDUFA2, NDUFS4)." (PMID 23028713, 2012).
schizophrenia (3 papers, 2020 to 2023). A major psychotic disorder characterized by abnormalities in the perception or expression of reality. "The mRNA level of NDUFA2 was most significantly associated with schizophrenia and the remission of psychiatric symptoms." (PMID 37168668, 2023).
breast carcinoma (2 papers, 2019 to 2024). "Other notable genes decreased by SK1 KD were NDUFA2 in prostate and E2F5, NAGK, VAPB, NFATC3, CDK2 in breast cancer cell lines." (PMID 30971929, 2019).
dementia (2 papers, 2022 to 2024). Loss of intellectual abilities interfering with an individual's social and occupational functions. "Mitochondrial function and the NDUFA2 gene are plausible mechanisms of action in dementia protection." (PMID 35902387, 2022). "This implies that the prioritised gene, NDUFA2, can be considered as a potential drug target for dementia prevention, both dependent on and independent of metformin’s action." (PMID 35902387, 2022).
Leukoencephalopathy (2 papers, 2020 to 2022). This term describes abnormality of the white matter of the cerebrum resulting from damage to the myelin sheaths of nerve cells. "Mutations in NDUFA2 have also been reported to be associated with complex 1 deficiency resulting in leukoencephalopathy." (PMID 36499081, 2022).
Cognitive impairment (1 paper, 2024). Abnormal cognition is characterized by deficits in thinking, reasoning, or remembering. "In participants with cognitive impairment, the expression levels of KEGG:M00146’s NDUFA2, NDUFA3, NDUFA4, NDUFA6, NDUFA7, NDUFA10, and NDUFA12 increased, but the expression levels of NDUFA5, NDUFA4L2, and NDUFAB1 marginally decreased." (PMID 38542318, 2024).
depression (1 paper, 2021). "Several TWAS significant genes were also dysregulated in brains of depression cases compared with controls (including PCDHA8, FANCL, TMEM161B-AS1, GMPPB, STAU1, NDUFA2, GPX1 and PCDHA7), implying that genetic variants may contribute to depression risk by regulating gene expression." (PMID 34021117, 2021). "Interestingly, five TWAS significant genes (TMEM161B-AS1, GMPPB, STAU1, NDUFA2 and GPX1) were significantly upregulated in brains of depression cases compared with controls in GSE102556 dataset." (PMID 34021117, 2021).
female infertility (1 paper, 2021). Diminished or absent ability of a female to achieve conception. "In summary, our findings suggested that p62 deficiency in the pituitary led to female infertility via impaired LH, illustrating the GnRH-p62-OXPHOS (Ndufa2)-ATP-LH pathway in gonadotropic cells and highlighting the role of pituitary p62 in the female reproductive system." (PMID 34453106, 2021).
head or neck paraganglioma (1 paper, 2022). "Other studies have shown that deregulated expression of NDUFA2 is associated with mitochondrial dysfunction which can contribute to the development of a head or neck paraganglioma." (PMID 36499081, 2022).
larynx squamous cell carcinoma (1 paper, 2022). "We observed a gene cluster, containing three genes (UQCRQ, NDUFA2, and NDUFS4) with different expression in various tumor stages of larynx squamous cell carcinoma, in modules related to tumor stage." (PMID 35715770, 2022).
leukodystrophy (1 paper, 2020). Leukodystrophies are a group of rare, progressive, metabolic, genetic diseases that affect the brain, spinal cord and often the peripheral nerves. "Herein, we report a further female child affected by NDUFA2-related disorder presenting with cavitating and tigroid-like pattern of leukodystrophy and without systemic biochemical abnormalities of mitochondrial disorders." (PMID 32154054, 2020).
mental disorder (1 paper, 2020). A disease that has its basis in the disruption of mental process. "Three (COX5B, SEC62, and NDUFA2) were validated with another technique and were also differentially regulated in postmortem brain of subjects with mental disorders." (PMID 32184383, 2020).
rectum adenocarcinoma (1 paper, 2022). An adenocarcinoma arising from the rectum. "On the other hand, in rectum adenocarcinoma, the upregulation of NDUFA2 was a highly unfavorable factor, presenting a 19% 5-year survival rate in comparison to 67% for the NDUFA2 low-expression cohort." (PMID 35885025, 2022).
renal failure (1 paper, 2009). "Interestingly, another gene encoding for a subunit of this complex (NDUFA2) was identified by microarray analysis being up-regulated in skeletal muscle biopsy specimens of HD patients compared to control subjects without renal failure." (PMID 19698090, 2009).
cancer (3 papers, 2021 to 2024). A tumor composed of atypical neoplastic, often pleomorphic cells that invade other tissues. "For example, our analysis revealed increased expression of NDUFA2 and UQCRQ, all key components of the mitochondrial respiratory chain, in LGHO group in 25/33 cancer types." (PMID 34030708, 2021).
neurodegenerative disease (1 paper, 2023). A disorder of the central nervous system characterized by gradual and progressive loss of neural tissue and neurologic function. "Ultimately, the temporal dynamics of the expression profiles of genes associated with neurodegenerative diseases, such as Ndufa2, Ndufb6, Snca, Ndufb8 and Cox8a, were characterized by trending." (PMID 37834317, 2023).
NDUFA2 also shares sentences with these, for which no sentence is quoted: Huntington disease (3 papers); infection (3); Parkinson disease (2); tumor (2); cardiac hypertrophy (1); cervical cancer (1); COVID-19 (1); glaucoma (1); leukemia (1); liver diseases (1); paraganglioma (1); Sepsis (1).